CRP (C-reactive protein)
Diseases named in the same sentence as CRP in open-access papers (continued):
Sharing a sentence is not in itself a finding about the gene and the disease.
acute pancreatitis (continued). "In recent years, there have been observations that CRP level >150 mg/L within 48 hours of symptoms onset correlates with the expected severity of the acute pancreatitis." (PMID 26784348, 2016). "Serum PCT measurements have been reported to be superior to C-reactive protein in discriminating infectious from other inflammatory diseases, such as acute pancreatitis, cardiogenic shock and acute transplant rejection." (PMID 25887691, 2015). "Taken together, these data show that CRP serum levels at the day of admission best predict the course of acute pancreatitis." (PMID 23342125, 2013). "As a whole CRP is a good marker for prediction of complications and mortality in acute pancreatitis." (PMID 24204087, 2013). "Serum BAFF correlates with CRP, an established marker of severity in acute pancreatitis at day of admission with a timecourse profil similar to IL-6 over the first nine days." (PMID 23342125, 2013). "As a single prognostic marker, an elevated C-reactive protein (CRP) concentration of greater than 150 mg/L indicates that acute pancreatitis has a complicated course with a sensitivity of 85% in the first 72 h after the onset of symptoms." (PMID 24204087, 2013). "Overall CRP seems to be the best characterized predictive parameter in acute pancreatitis and therefore is the established “gold standard” when testing new potential predictive parameters." (PMID 23342125, 2013). "Patients with predicted severe acute pancreatitis (Imrie-score ≥ 3 or APACHE-II score ≥ 8 or CRP > 150 mg/L) will be randomised to EN within 24 hours or an oral diet and EN if necessary, after 72 hours after hospital admission." (PMID 21392395, 2011). "The present study aimed to assess Interleukin-8 (IL-8), C-reactive protein, and tumor necrosis factor-α as prognosticators of a severe course of acute pancreatitis." (PMID 20130823, 2009). "IL-8 in early phase of acute pancreatitis is superior marker compared to CRP and TNF-α for distinguishing patients with severe disease." (PMID 20130823, 2009). "Chylomicron and very low-density lipoprotein (VLDL) have been shown to develop calcium-dependent agglutination by C-reactive protein in acute pancreatitis." (PMID 18577211, 2008). "In another study, serum matrix metalloproteinase 9 (MMP9) levelin severe acute pancreatitis was positively correlated with TNFα and CRP levels." (PMID 18670651, 2008). "Patients eligible for randomisation are adult patients with a first onset of predicted severe acute pancreatitis: Imrie criteria 3 or more, CRP 150 mg/L or more, APACHE II score 8 or more." (PMID 15456517, 2004). "Previous studies mostly focused on the assessment of the prognosis of acute pancreatitis by traditional scoring systems (such as APACHE II score) or single biomarkers (such as CRP), but these methods have certain limitations in predicting persistent renal failure." (PMID 41249998, 2025). "Interestingly, our study’s discriminative value of CRP is equivocal, showing an inversely related prediction of acute pancreatitis severity grade." (PMID 38255211, 2024). "Similarly, another study analyzing 169 patients with acute pancreatitis highlighted FPR as a superior prognostic indicator compared to CRP in predicting the prognosis of these patients." (PMID 38915920, 2024). "Univariate logistic regression analysis identified several factors associated with early encapsulation in acute pancreatitis, including the time from onset to CECT examination, C-reactive protein level, alanine aminotransferase level, total bilirubin, creatinine level, and APACHE II score." (PMID 38287237, 2024). "CRP, calcium, and albumin are predictive factors for severe acute pancreatitis." (PMID 38459563, 2024). "CRP at admission was raised in 34.1% of total cases of acute pancreatitis in our study." (PMID 37203982, 2023). "CRP > 150 mg/L suggests a complex course of acute pancreatitis." (PMID 38093973, 2023).
acute pancreatitis (continued). "In addition, levels of other markers used to monitor COVID-19 disease, including CRP, ferritin, lactate dehydrogenase, and D-dimer were higher among patients who subsequently developed acute pancreatitis." (PMID 37436286, 2023). "This study aimed to identify whether interleukin-6 (IL-6) is better than C-reactive protein (CRP) for the prediction of severe acute pancreatitis (SAP), infected pancreatic necrosis (IPN), and mortality." (PMID 36467730, 2022). "We believe the CRP/albumin ratio is easy to calculate and gauge the severity of acute pancreatitis." (PMID 36262941, 2022). "There is sparse literature on evaluating the role of the CRP/albumin ratio in acute pancreatitis." (PMID 36262941, 2022). "With the ever-evolving use of the acute-phase reactant protein, C-reactive protein (CRP), and an abundant circulating protein in plasma, albumin, in daily practice, this study aimed to assess the ratio of CRP and albumin for assessing the severity of acute pancreatitis." (PMID 36262941, 2022). "Moreover, CRP had a good prognostic accuracy not only for severe acute pancreatitis but also pancreatic necrosis and in-hospital mortality." (PMID 36057565, 2022). "The current study assesses the value of CRP at different intervals and cut-offs in predicting complicated acute pancreatitis (CAP) and compares its performance against other available predictors like neutrophil to lymphocyte ratio (NLR); Glasgow scoring system and modified CT severity index (MCTSI)." (PMID 34900460, 2021). "Our objective was to evaluate whether serum CRP and cPLI concentrations are useful biomarkers for assessing clinical changes in hospitalized dogs with acute pancreatitis." (PMID 34250650, 2021). "Nevertheless, CRP levels measured 48–72 h following initial presentation might correlate with acute pancreatitis outcome." (PMID 34256804, 2021). "Many dogs in our study had concurrent diseases, so it is difficult to determine whether serum CRP concentration was affected by acute pancreatitis or the concurrent conditions." (PMID 34250650, 2021). "In addition to serum concentrations of CRP and cPLI, we used both of these scoring systems to standardize the clinical evaluation of dogs with acute pancreatitis." (PMID 34250650, 2021). "Results of the current study show that CRP at admission had very poor diagnostic accuracy and was almost nonpredictive of complicated acute pancreatitis." (PMID 34900460, 2021). "Serum cPLI and possibly CRP could be used as objective biomarkers for clinical changes in hospitalized dogs with acute pancreatitis." (PMID 34250650, 2021). "We hypothesized that serum CRP and cPLI concentrations would decrease during hospitalization in conjunction with clinical improvement, as dogs recovered from acute pancreatitis as assessed using the MCAI and the CAPCSI." (PMID 34250650, 2021). "As a result of meta-analysis, 24-48 of CRP in acute pancreatitis." (PMID 33489590, 2020). "Indeed, CRP is a common marker of disease severity with good prognostic accuracy for severe acute pancreatitis." (PMID 31647014, 2019). "The CRP/albumin ratio has been shown as a predictor of mortality in acute pancreatitis patients." (PMID 30297655, 2018). "Taken together, results up to this point support the hypothesis that BAFF has characteristics of an acute phase protein like CRP and shows prognostic value in acute pancreatitis." (PMID 23342125, 2013). "However, it needs to be emphasized that our study also confirmed CRP as the “gold standard” for predicting severity of acute pancreatitis." (PMID 23342125, 2013). "Combined assessment of CRP, PCT, IL-6 and LDH achieves an area under the curve (AUC) of 0.98, indicating excellent diagnostic performance for the early identification of severe acute pancreatitis (SAP) and highlighting the potential of multimarker panels in clinical practice." (PMID 41208148, 2025).
acute pancreatitis (continued). "Therefore, the researchers point out that measuring C3a levels is a sensitive parameter and may be a better alternative to CRP for predicting severe acute pancreatitis." (PMID 37509709, 2023). "CRP/albumin ratio could be used to predict prognosis in patients with acute pancreatitis." (PMID 36262941, 2022). "Therefore, in the absence of other clinical signs and suspicion of early posttransplant infection in the patient, elevated CRP levels within the first 72 hours postoperatively represent a fairly specific marker for pancreatic tissue injury comparable to other forms of acute pancreatitis." (PMID 35743457, 2022). "Also, it is reported that the level of CRP is related to the severity of acute pancreatitis." (PMID 34093703, 2021). "In summary, we note that NEFA may cause acute hypocalcemia in critical illnesses, and extracellular calcium supplementation by Ringer’s lactate may contribute to the early clinical improvement in systemic inflammatory response and C-reactive protein noted during severe acute pancreatitis." (PMID 31963691, 2020). "However each of PLR, glucose, and CRP is essential in acute pancreatitis." (PMID 33489590, 2020). "Therefore, out of the determined inflammatory markers at the day of admission, BAFF, PCT and CRP serum levels might have a predictive value for the course of acute pancreatitis." (PMID 23342125, 2013). "Other studies over the last few years have suggested that serum levels of interleukins and TNF-α may be used to identify patients who are prone to develop local or systemic complications and were compared with CRP which has been employed in the prediction of severity of acute pancreatitis." (PMID 20130823, 2009). "Recent studies have suggested that the serum levels of interleukins and TNF-α may be used to identify patients who are prone to develop local or systemic complications and were compared with CRP which has been employed in the prediction of severity of acute pancreatitis." (PMID 20130823, 2009). "In multivariate analysis, the model including the following independent parameters was predictive for the severity of acute pancreatitis: CTSI score (p < 0.0001), BISAP score (p = 0.0082), and CRP levels at 48 h (p = 0.0091), respectively." (PMID 39857010, 2025). "HR: heart rate; RR: respiratory rate; SpO2: oxygen saturation; Temp: temperature; GCS: Glasgow Coma Scale; BUN: blood urea nitrogen; CRP: C-reactive protein; IQR: interquartile range; AP: acute pancreatitis; TLC: total leukocyte count." (PMID 41523376, 2025). "ROC analysis results for important biochemical parameters showed that both parameters (CRP and WBC) had high discrimination power from patients with acute pancreatitis." (PMID 40282999, 2025). "In acute pancreatitis, LDH showed higher sensitivity (94.9%) but lower specificity (88.2%) compared to CRP (sensitivity of 59.0% and specificity of 97.4%)." (PMID 40563651, 2025). "A retrospective analysis carried out on 108 patients with acute biliary pancreatitis showed the BISAP score (AUC 0.91), CRP levels at 48 hours (AUC 0.92), MCTSI (AUC 0.94), and CTSI (AUC 0.93) had the highest AUC for predicting the severity of AP." (PMID 41446633, 2025). "This study investigated the effects of different early resuscitation fluid replenishment rates (FRRs) on inflammation (serum interleukin-6 (IL-6) and C-reactive protein (CRP), PCT and complications in patients with severe acute pancreatitis (SAP)." (PMID 40951887, 2025). "SIG, CRP, PNI, and WBC represent promising early prognostic markers for severe acute pancreatitis (SAP)." (PMID 40672827, 2025). "However, few studies have determined which factors might relate to a longer length of stay of patients with acute pancreatitis except for those with a higher severity score using the revised Atlanta classification and some biomarkers such as the C reactive protein/albumin ratio." (PMID 38248369, 2024).
acute pancreatitis (continued). "Recently, the magnetic resonance severity index (MRSI) has been proposed for the diagnosis of acute pancreatitis, and it correlates significantly with Ranson's scores, CTSI, C-reactive protein (CRP) levels, hospital admission intervals, and clinical prognosis." (PMID 39512989, 2024). "Elevated serum suPAR, together with c-reactive protein (CRP), has also been shown to correlate with the severity of acute pancreatitis." (PMID 39540961, 2024). "In murine models of acute pancreatitis, PFD treatment resulted in reduced serum levels of HMGB1 and C-reactive protein, two inflammatory markers that have been linked to poor outcomes in clinical studies of epilepsy." (PMID 39911825, 2024). "Biochemical markers such as CRP and PCT have proven valuable in distinguishing between mild and severe cases of acute pancreatitis, facilitating early complication identification and guiding appropriate treatment approaches." (PMID 39011189, 2024). "Serum ferritin in the early stage of acute pancreatitis is one of the biomarkers of inflammation and, in association with the ferritin-to-hemoglobin ratio, stands out as a predictor of a negative outcome, next to standard serum markers such as CRP, D-dimers, procalcitonin, or fibrinogen." (PMID 38255211, 2024). "Patients with severe acute pancreatitis (SAP) were significantly older, more likely to be female, and had higher CRP levels, lower albumin, and higher CRP/albumin ratios compared to mild acute pancreatitis patients." (PMID 38283464, 2023). "Some studies have suggested that the risk factors for acute pancreatitis after pancreatic resection include being a woman, not having received neoadjuvant therapy, and the presence of a soft pancreatic texture, a small main pancreatic duct diameter, or high C-reactive protein levels." (PMID 37228763, 2023). "The results of univariate logistic regression analysis showed that BISAP, CRP, PCT, MCTSI, and rad-score were significant factors in differentiating the progression of acute pancreatitis." (PMID 38093973, 2023). "We assessed three tests, namely CRP, PCT, and LDH, all within two weeks of symptom onset of acute pancreatitis." (PMID 36611486, 2022). "We hypothesized that serum CRP and cPLI concentrations would decrease during hospitalization in association with clinical improvement as dogs recovered from acute pancreatitis, as assessed by the MCAI and the canine acute pancreatitis clinical severity index (CAPCSI)." (PMID 34250650, 2021). "A retrospective analysis reported that the CRP and NLR levels were increased in acute pancreatitis patients." (PMID 34915876, 2021). "Our study aimed to explore the role of BUN changes, compared with APACHE-II, haemoconcentration, and C-reactive protein (CRP), in predicting mortality and severity in patients diagnosed with acute pancreatitis." (PMID 33824864, 2021). "Increases in the levels of serum C-reactive protein (CRP) and creatinine (Cr) and decreases in those of albumin (Alb) are commonly observed in acute pancreatitis (AP)." (PMID 33298030, 2020). "We aimed to explore the significance of procalcitonin (PCT), C-reactive protein (CRP) and neutrophil ratio (N%) in the early diagnosis, treatment, and prognosis of severe acute pancreatitis (SAP)." (PMID 31993385, 2019). "C-reactive protein level (CRP) and white blood cell count (WBC) have been variably used in clinical trials on acute pancreatitis (AP)." (PMID 31551798, 2019). "Discriminant analysis was performed to further investigate the value of serum BAFF, IL-6, CRP, PCT, and leukocyte counts measured at the day of admission to predict a severe course of acute pancreatitis (sNPoD)." (PMID 23342125, 2013). "This is a study limitation, as CRP is not synonymous with clinically defined severe acute pancreatitis (e.g., according to the Revised Atlanta Classification)." (PMID 41597402, 2026).
acute pancreatitis (continued). "A dual perspective on pathophysiology: Unlike single-concept scores, our scale is deliberately designed to reflect the two main drivers of severe acute pancreatitis: local pancreatic injury (measured by TAP and trypsin-2) and systemic inflammatory response (measured by CRP and other markers)." (PMID 41517517, 2025). "In this comparative analysis of 179 patients with severe acute pancreatitis, we observed that age above 60, elevated inflammatory markers (NLR, PLR, and CRP), higher severity scores (APACHE, Ranson, and the CTSI), and the presence of persistent organ failure strongly predict mortality." (PMID 40299332, 2025). "Previous studies have also shown that CRP in acute pancreatitis peaks not at the time of presentation but 36–72 h later." (PMID 39964633, 2025). "A meta-analysis targeting acute pancreatitis revealed that the sensitivity and specificity of PCT were lower than those of other biomarkers such as CRP or fecal calprotectin; however, it serves as a helpful adjunct in certain clinical scenarios to make appropriate treatment decisions." (PMID 40217585, 2025). "In our study, the accuracy of predicting the severity of acute pancreatitis was analyzed, and BISAP score at admission (AUC-0.91), CRP levels at 48 h (AUC-0.92), mCTSI (AUC-0.94), and CTSI score (AUC-0.93) had the highest area under the curve (AUC) for predicting the severity of acute pancreatitis." (PMID 39857010, 2025). "For example, CRP levels are used as a criterion to rule out, with a high probability, the presence of necrosis in acute pancreatitis." (PMID 39120614, 2024). "Additionally, CRP and PCT have demonstrated potential in distinguishing between mild and severe acute pancreatitis cases, with PCT exhibiting superior sensitivity and specificity compared to alternative tests." (PMID 39011189, 2024). "Clinical evidence showed that UTI had a significant effect on inflammatory biomarkers such as C-reactive protein (CRP), interleukin-6 (IL-6), and tumor necrosis factor-alpha (TNF-α), as well as reduced and prevented MODS and lowered mortality in acute pancreatitis." (PMID 35634310, 2022). "In the past, serum CRP and interleukin levels have been well evaluated for the assessment of the severity and prognosis of acute pancreatitis in “non-transplant” patients." (PMID 35566689, 2022). "Serum CRP levels are well evaluated for the assessment of the severity of acute pancreatitis in nontransplant patients." (PMID 35743457, 2022). "With a very low PPV, CRP at 48 hours at a cut-off value of 190 is also not a good predictor of complicated acute pancreatitis." (PMID 34900460, 2021). "Several serological biomarkers and scores have been described, namely C-reactive protein (CRP), hepcidin, procalcitonin (PCT), the systemic inflammatory response index (SIRI), the bedside index for severity in acute pancreatitis (BISAP), SIRS, and the modified Marshall score (MMS)." (PMID 34205667, 2021). "A previous study found that serum CRP concentration was not significantly different between the surviving and nonsurviving groups in dogs with acute pancreatitis until the third and fourth day of hospitalization." (PMID 34250650, 2021). "The wide range in the reported values in itself is evidence that CRP at 48 hours is not reliable in predicting complicated acute pancreatitis." (PMID 34900460, 2021). "Four guidelines recommend C-reactive protein as an indicator of the severity of acute pancreatitis, two of which provide specific reference values for CRP, two guidelines do not, and two guidelines do not provide evidence to support CRP." (PMID 33419464, 2021). "In a prospective study of 175 patients divided into mild and non-mild acute pancreatitis according to the Atlanta classification, CRP and IL-6 combined demonstrated good discriminative capacity with an area under the curve of 0.803." (PMID 31210778, 2019).